COL10A1 (collagen type X alpha 1 chain)
Diseases named in the same sentence as COL10A1 in open-access papers (continued):
Sharing a sentence is not in itself a finding about the gene and the disease.
tumor (continued). "The results shown that knockdown of COL10A1 drastically decreased the tumor growth of H1299 cells." (PMID 33324550, 2020). "The elevated expression of COL10A1 observed in tumors might be an indirect effect of higher-level regulatory alterations occurring in the tumor." (PMID 25215506, 2014). "However, COL10A1 was low expressed in 2 tumor types, comprising KICH and KIRP, which might be due to the diverse tumorigenic mechanisms." (PMID 37006317, 2023). "Comparing the gene signatures to the cancer-associated patient-specific MSCs isolated in our study provide evidence that the patient-derived cluster of cells (C7) had an increased level of COL10A1 expression; thus, these cells may be the source of COL10A1 expression in the tumor." (PMID 36940196, 2023). "COL10A1 transcription may mediate tumor cell interaction with its stromal microenvironment." (PMID 36267978, 2022). "Thus, COL10A1 is a specific marker potentially involved in tumor angiogenesis." (PMID 36246404, 2022). "Indeed, we could only identify one de novo tumor-specific protein, the collagen alpha-1(X) chain (COL10A1)." (PMID 35340765, 2022). "Moreover, using protein-based quantification of COL10A1 in tumor specimens based on histological staining and semi-quantitative signal quantification in 197 CRC patients, they identified the significant clinical negative prognostic value of an elevation of the biomarker." (PMID 36267978, 2022). "It was demonstrated that COL10A1 expression preceded the development of bone vascularization and then altered the properties of the extracellular matrix contributed to the invasion of blood vessels, and angiogenesis was particularly important for tumor tissues." (PMID 36246404, 2022). "High expression of COL10A1 in various solid tumor tissues may be related to tumor angiogenesis." (PMID 33371777, 2021). "Moreover, our results indicated that COL10A1 might promote tumor aggressiveness via upregulation of the TGF-β1-SOX9 axis." (PMID 30154451, 2018). "In CRC, the COL11A1 gene is excessively expressed and contributes to tumor advancement by upregulating other genes like THBS2, COL10A1, COL5A2, and COL1A2, thereby driving neoplasia." (PMID 40109582, 2025). "Through drug sensitivity prediction and experimental validation, we identified NU7441 as a small-molecule inhibitor reduced COL10A1 expression/secretion and attenuated CAF-mediated pro-tumor effects in preclinical models." (PMID 40826474, 2025). "PPI analysis revealed COL10A1, POSTN, SPP1, MMP11, and GREM1 as key hub genes in extracellular matrix (ECM) remodeling and tumor progression." (PMID 40826767, 2025). "To investigate the role of COL10A1+Fib in promoting the malignant progression of CRC, we comprehensively assessed their effects on tumor cell phenotypes." (PMID 40826474, 2025). "Compared with normal tissues, the top three downregulated genes in the tumor tissues were FABP4, SAA1, and SFRP1, while the top three upregulated genes were COMP, COL10A1, and MMP11." (PMID 40936892, 2025). "Functionally, COL10A1+Fib significantly promoted the migration of M0 macrophages and localized near CD163+ and CD206+ M2 macrophages (Primary Tumor: n = 35)." (PMID 40826474, 2025). "The TCGA and GETx datasets indicated that COL1A1, COL3A1, COL5A2, COL8A1, COL10A1, and COL12A1 genes were expressed much higher in tumor tissues than in the normal ones." (PMID 36900272, 2023). "We then analyzed the correlation between COL10A1/FAP/FN1 and tumor immune cells, and the outcomes showed that FAP had significant positive correlations with macrophages, Th1 cells, neutrophils, iDC, Tgd, TReg, mast cells, and NK cells (R > 0.4, P < 0.001)." (PMID 38063927, 2023). "Based on the previous significant differences in the expression levels of the two subtypes of C1 and C2 immune checkpoints, we further investigated the correlation between COL10A1/FAP/FN1 and tumor immune checkpoints." (PMID 38063927, 2023).
tumor (continued). "TIMER analysis showed that DNAJB1, COL10A1, PTGS2, AFP, and EGF were correlated with tumor-infiltrating lymphocytes." (PMID 36967783, 2023). "To receive further insights in the clinical translation relevance of COL10A1 in CRC, we performed another screening of COL10A1 activation level with parameters typical describing advanced tumor cell invasion." (PMID 36267978, 2022). "Our results on protein expression using western blot assay also showed an increase in COL10A1, BGN, and FAP proteins in tumor tissue compared with adjacent normal tissue, consistent with staging." (PMID 35328635, 2022). "Our results suggested that the four mRNA vaccine targets, namely, ADAMTS18, COL10A1, PPEF1, and STRA6, were positively correlated with the infiltration of dendritic cell, thereby activating cytotoxic T cells against tumor cells." (PMID 35874675, 2022). "For ADAMTS12, AEBP1, COL10A1, COL11A1, CXCL11, EPPK1, and WNT7B, their expression values were higher in tumor samples than in normal samples." (PMID 35505821, 2022). "The infiltration of macrophages, neutrophils, and dendritic cells are positively correlated with these COL8A1, COL10A1, CTHRC1, and FAP, suggesting the need for exploration of their roles in the tumor microenvironment of GC." (PMID 35910202, 2022). "The expression of COL8A1, COL10A1 and COL17A1 were found to be significantly elevated in many different tumor types 30-34 and they were all tumor-related genes." (PMID 33753985, 2021). "Among them, the expression of COL1A1, COL10A1, and COL11A1 were found to be particularly high in tumor tissues compared with normal counterpart; on the contrary, the expression of COL4A4, COL6A5 and COL14A1 was significantly lower in tumor tissues." (PMID 34199373, 2021). "Cluster 2 was primarily driven by Col10a1 expression (relative contribution to meta-gene = 0.89), a potential marker of CD10+ tumor stromal cells, and cluster 4 showed some enrichment for mesenchymal stem cell markers (p = 1.01E–08)." (PMID 26980748, 2016). "Our data also demonstrates significant up-regulation of COL11A1, COL10A1, MMP1 and MMP13, and significant down-regulation of COL6A6 and DLK1 in tumor relative to non-tumor adjacent breast tissue." (PMID 27857161, 2016). "COL11A1, COL10A1, MMP1 and MMP13 are highly expressed in aggressive molecular subtypes (basal and HER2 tumors) in the Lebanese as their expression increases tumor migration and proliferation." (PMID 27857161, 2016). "Although our findings suggest a multifaceted role for COL10A1 in the maintenance and remodeling of the ECM with involvement of CAFs, immune cells, and other key players in the tumor microenvironment, they are necessarily limited by the descriptive nature of this study." (PMID 39939916, 2025). "Functionally, COL10A1 contributes to ECM remodeling and can interact with proteins such as prolyl 4-hydroxylase subunit beta (P4HB) and integrin subunit beta 1 (ITGB1) to facilitate tumor cell proliferation and metastasis." (PMID 40826474, 2025). "Finally, we identified that COL10A1 is an unfavorable factor for BLCA, and its expression is significantly connected with the tumor-infiltrating immune cells." (PMID 37006317, 2023). "Of these, HS6ST2, COL10A1, and NQO1 were significantly up regulated in tumor tissues." (PMID 35260044, 2022). "Our in silico study reveals that an abundance of COL11A1 mRNA could induce the transcriptional upregulation of THBS2, COL10A1, COL5A2, and COL1A2 genes cooperatively, to promote the neoplasia." (PMID 33597969, 2021). "In general, the expression of P3H2, COL10A1, and C5 in tumor tissues was significantly increased than that in normal tissues, and the expression of UHRF1, considered as a tumor suppressor gene, was higher in normal tissues than in tumor tissues." (PMID 33934516, 2021). "COL10A1 and SPP1 were upregulated in tumor tissues, and SGCG was downregulated." (PMID 33324550, 2020).
tumor (continued). "The protein expression levels of COL10A1 and SOX9 were significantly correlated with tumor size (P = 0.016 and P = 0.023), tumor differentiation (P = 0.005 and P = 0.022), lymph node metastasis (P = 0.004 and P = 0.001), and serosal invasion (P = 0.001 and P = 0.015)." (PMID 30154451, 2018). "For six of the genes (CCT5, CD72, COL10A1, FAM177A1, SLC25A12 and TDP1), we were unable to identify a correlation (i.e. concordance) between the copy number alteration and gene expression in six of the tumour samples tested." (PMID 25884485, 2015). "Notably, the molecular and spatial properties of COL10A1+Fib strongly resemble this “pan-cancer” CAF state, suggesting that COL10A1+Fib supporting the possibility that COL10A1+Fib constitutes a recurrent CAF subset in diverse tumor contexts." (PMID 40826474, 2025). "COL10A1 secreted by CAFs could facilitate LUSC cell proliferation and repress apoptosis-induced oxidative stress, and the mechanism was due to elevated expression mediated by METTL3 promoting its mRNA m6A modification, thereby accelerating tumor growth." (PMID 36246404, 2022). "Only the expression of COL10A1 and MMP11 was found to progress from ‘low expression’ in pDCIS, to ‘intermediate expression’ in DCIS and ‘high expression’ in the corresponding IBC, the difference between pDCIS and DCIS (of DCIS/IBC mixed tumours) being significant (P < 0.05)." (PMID 30236106, 2018). "Tissues analyzed demonstrated significant up-regulation of COL11A1 and COL10A1 in tumor tissue as compared to non-tumor adjacent tissue in the Lebanese, suggesting that both proteins might play a role in local invasion of BC cells." (PMID 27857161, 2016).
cancer (63 papers, 2010 to 2026). A tumor composed of atypical neoplastic, often pleomorphic cells that invade other tissues. "COL10A1 is an extracellular matrix-related protein and has been associated with cancer-associated fibroblasts." (PMID 38638443, 2024). "Subsequently, using Weighted Gene Co-expression Network Analysis (WGCNA), we discovered that SYNPO2L can regulate COL10A1, mediating the actions of Cancer-Associated Fibroblasts." (PMID 39247832, 2024). "Another CC term, extracellular matrix (associated with the HubGs COL11A1 and COL10A1), is involved in the development and progression of cancer and is effective for cancer therapy." (PMID 37893423, 2023). "Cox regression showed that COL10A1 was associated with PFS in five cancer types: GBM (p = 1.43E-04, HR = 1.684), KIRC (p = 1.86E-05, HR = 1.409), KIRP (p = 7.48E-07, HR = 2.289), PAAD (p =0.006, HR = 1.172) and PRAD (p = 0.003, HR = 1.283)." (PMID 38147021, 2023). "Meanwhile, using the cBioPortal database, COL10A1 mutations was screened in different cancers and 12 missense sites between amino acids 0 and 680 was identified." (PMID 38147021, 2023). "Using the TISIDB database, we continued to investigate the association between COL10A1 level and immunophenotyping and molecular typing of different types of cancer." (PMID 38147021, 2023). "AEBP1 is a marker of cancer-associated fibroblasts, and high expression of COL10A1 was associated with unfavorable prognosis in CRC21." (PMID 37500893, 2023). "Same as before, our latest study showed that COL10A1 was strongly upregulated in the majority of cancers, and that high COL10A1 expression was associated with a worse cancer prognosis." (PMID 38147021, 2023). "COL10A1 is poorly expressed in a variety of normal tissues, suggesting the potential utility of this gene as a diagnostic marker and therapeutic target for cancers." (PMID 36105715, 2022). "Transcriptomic alignment noted a strong positive correlation of COL10A1 with transcriptomic signature of cancer-associated fibroblasts (CAFs) and populations of the immune compartment, namely, B cells and macrophages." (PMID 36267978, 2022). "Taken together, the molecular mechanisms underlying COL10A1-enhanced cancer cell invasion were elucidated, providing an understanding of novel diagnostic and therapeutic strategies." (PMID 30154451, 2018). "Also, a pan-cancer-based survival analysis demonstrated that COL10A1 was a risk factor for most cancers, and an elevated COL10A1 expression usually indicated a poor prognosis for patients (especially in KIRC, KIRP, STAD, PAAD, SARC, PRAD and UCEC)." (PMID 38147021, 2023). "Both cancer types are enriched in stroma, and COL10A1 implicates bone marrow-derived fibroblasts as contributors to the epithelial-to-mesenchymal transition (EMT) in these tumors." (PMID 39939916, 2025). "COL8A1 is highly expressed in OA tissues and, like COL10A1, is a myofibroblastic-specific marker in cancer." (PMID 39939916, 2025). "In accordance with these observations, we focused on BRCA and PAAD tumors to evaluate the impact of COL10A1 on cancer pathophysiology." (PMID 39939916, 2025). "Together, these results suggest a shared activation of common EMT-related pathways in cancer, bone marrow, and pathological OA contexts, highlighting the role of COL10A1 as a marker of both BMSCs and pro-metastatic tumors." (PMID 39939916, 2025). "In summary, our multi-omics pan-cancer analysis reveals the widespread presence of COL10A1+Fib across solid tumors." (PMID 40826474, 2025). "Pan-cancer analyses suggest that COL10A1+Fib is enriched in several solid tumors, highlighting its potential as a therapeutic target." (PMID 40826474, 2025). "Pan-cancer analysis suggested that COL10A1+Fib is prevalent in multiple solid tumors and displays similar transcriptomic features." (PMID 40826474, 2025).
cancer (continued). "In particular, FN1, VCAN, and LRRC15 are markers of BMSCs which also co-modularized with COL10A1 in cancer; all three genes are involved in cell migration, and FN1 contributes directly to osteoblast mineralization as well as metastasis." (PMID 39939916, 2025). "The top five upregulated genes (MMP1, COL10A1, CXCL8, TM4SF1 and PLAU) have been associated with cancer progression and metastasis-inducing mechanisms." (PMID 40640495, 2025). "The identification of genes with high functional similarity to known biomarkers, such as MATN2 to COL10A1, opens new avenues for research into the roles of these genes in cancer progression." (PMID 40004168, 2025). "To systematically evaluate the distribution and functional characteristics of COL10A1+Fib across cancers, we integrated multi-omics data from ten high-mortality solid tumors (including CRC)." (PMID 40826474, 2025). "The upregulation of COL10A1, which is a distinct cleavage product of type X collagen, is prominent in malignant tumors and holds a pivotal role in the development and advancement of tumors." (PMID 40092988, 2025). "Cancer-associated fibroblasts (CAF) expressed well-known markers including FAP, COL1A1, COL10A1, MMP11, and CTHRC120,21, and other genes such as INHBA, SLC12A8, F2R, and COL12A1 in various organs." (PMID 38744958, 2024). "The largest group of TAAs (n = 14) derived from genes reported as markers of cancer-associated fibroblasts (CAFs) (COL11A1, COL10A1, LRRC15)." (PMID 37906288, 2024). "Upregulated COL10A1 expression is associated with the invasion, migration, and EMT processes of cancer cells." (PMID 38345033, 2024). "Pan-cancer characterization of expression based on the TCGA database showed that COL10A1 was significantly overexpressed in 13 cancer types than in normal tissues." (PMID 37006317, 2023). "Subsequently, PrognoScan was employed to evaluate the relationship between COL10A1 and the prognosis of each type of cancer." (PMID 38147021, 2023). "Lastly, the expression disparities of COL10A1 in various cancer types were assessed using TIMER database." (PMID 38147021, 2023). "In this study, we jointly analyzed the expression level of COL10A1 in pan-cancer using R software as well as online databases." (PMID 38147021, 2023). "The relationship between immune cell infiltrated and COL10A1 levels in pan-cancer was assessed using the TIMER database." (PMID 38147021, 2023). "The present research explored the impact of aberrant COL10A1 expression on cancer progression, as well as on patient prognosis, and warrants further research from investigators." (PMID 38147021, 2023). "Our team demonstrated that COL10A1 expression was strongly different between most cancers and normal tissues." (PMID 38147021, 2023). "The expression of COL10A1 and its prognostic significance across different cancer types was assessed using various databases including TCGA, PrognoScan, Kaplan-Meier plotter, and TIMER." (PMID 38147021, 2023). "The TISIDB database was then utilized to investigate the relationship between COL10A1 and immune and molecular features in various types of cancer." (PMID 38147021, 2023). "Collagen type X alpha 1 (COL10A1) is a structural component of the extracellular matrix that is aberrantly expressed in a variety of cancer tissues." (PMID 36105715, 2022). "A panel of RNAs prepared from various cancers and cancer cell lines were screened, finding the frequent upregulation of COL10A1 in various cancers." (PMID 36276283, 2022). "We finally validated the promoting role of COL10A1 in cancer development by validating it against several different databases." (PMID 36105715, 2022). "COL10A1, a collagen-type X alpha 1 chain, is elevated in multiple cancers including the lung, stomach, breast, colon, pancreas, and bladder." (PMID 35692369, 2022).